SHMT1 (serine hydroxymethyltransferase 1)
Diseases named in the same sentence as SHMT1 in open-access papers (continued):
Sharing a sentence is not in itself a finding about the gene and the disease.
lymphoma (3 papers, 2012 to 2025). A malignant (clonal) proliferation of B- lymphocytes or T- lymphocytes which involves the lymph nodes, bone marrow and/or extranodal sites. "Our lymphoma and adenoma data cast doubt on the utility of developing targeted interventions against Ldha, Phgdh and Shmt1." (PMID 22438825, 2012).
neural tube defect (3 papers, 2018 to 2025). A congenital defect characterized by failure of the neural tube to close completely; this results in the presence of openings in the brain or spinal cord. "Using intrauterine, maternal, and paternal groups and both triad and family approaches, it has been shown that the interaction between maternal and paternal SHMT1 C1420T predisposes the fetus to neural tube defects." (PMID 35098008, 2021). "Dietary deoxyuridine and uridine have been shown to have opposing effects on neural tube defect (NTD) incidence in the serine hydroxymethyltransferase 1 (Shmt1+/–) mouse model of folate-responsive NTDs, which are mediated by changes in de novo thymidylate biosynthesis." (PMID 29955725, 2018).
non-Hodgkin lymphoma (3 papers, 2015 to 2023). Distinct from Hodgkin lymphoma both morphologically and biologically, non-Hodgkin lymphoma (NHL) is characterized by the absence of Reed-Sternberg cells, can occur at any age, and usually presents as a localized or generalized lymphadenopathy associated with fever and weight loss. "A study of 7,309 patients with non-Hodgkin’s lymphoma showed that the SHMT1 C1420T polymorphism may be associated with the risk of developing non-Hodgkin’s lymphoma." (PMID 37147729, 2023).
pancreatic cancer (3 papers, 2018 to 2025). "Compared with SHMT2, the biological role of SHMT1 in pancreatic cancer remains poorly understood." (PMID 40738465, 2025). "Although the L474F site of SHMT1 was not confirmed to have a direct protective effect against pancreatic cancer, the study suggested that the loss of SHMT1 nuclear localization may be compensated by SHMT2 through metabolic mechanisms, thereby playing a role in the tumor environment." (PMID 40738465, 2025). "As such, one might predict that expression of this SNP would confer a protective effect against development of pancreatic cancer; however, expression of a cytoplasmic isozyme of SHMT2, SHMT2α, appears to functionally compensate for lack of wild-type SHMT1 protein." (PMID 29474406, 2018).
rectal carcinoma (3 papers, 2010 to 2015). A malignant epithelial neoplasm that arises from the rectum and invades through the muscularis mucosa into the submucosa. "The rectal cancer risk was significantly lower for SHMT1 TT (OR = 0.57, 95% confidence interval (CI) 0.36-0.89) and higher for MTHFR CT genotypes (OR = 1.4, 95%CI 1.06-1.84)." (PMID 20920350, 2010). "As expected from genotype analysis, the SHMT1 T allele/MTHFR CC diplotype was associated with reduced rectal cancer risk (OR 0.56, 95%CI 0.42-0.77 vs all other diplotypes together)." (PMID 20920350, 2010). "This is the first study presenting the protective effect of SHMT1 1420T allele or SHMT1 1420 T allele/MTHFR 677 CC diplotype against rectal cancer risk." (PMID 20920350, 2010). "The univariate comparison of raw genotype distributions of cases and controls revealed significant difference only in case of rectal cancer for both SHMT1 C1420T and MTHFR C677T polymorphisms." (PMID 20920350, 2010). "In the present study the combination of the SHMT1 1420CT+TT and MTHFR 677CC genotypes was found to imply the lowest risk for rectal cancer." (PMID 20920350, 2010). "An opposite distribution shift from variant homozygotes toward wild type and from wild type to hetorozygotes was present in case of SHMT1 and MTHFR, respectively, hence the SHMT1 CT+TT/MTHFR CC diplotypes were significantly underrepresented among cases with rectal cancer." (PMID 20920350, 2010). "As the distribution of SHMT1 C1420T genotypes are not available for the Hungarian population the European genotype frequencies and rectal cancer incidences were used instead to gauge any potential population stratification bias." (PMID 20920350, 2010).
Stroke (3 papers, 2011 to 2025). Sudden impairment of blood flow to a part of the brain due to occlusion or rupture of an artery to the brain. "SHMT1 methylation was also associated with Hcy in stroke cases (stroke cases, p = 0.034, controls, p = 0.950; total, p = 0.011) and HDL in controls (stroke cases, p = 0.146, controls, p < 0.0001, total, p = 0.001) using regression analysis adjusted for age, sex, BMI, Hcy, HDL, and LDL." (PMID 33259775, 2021). "This suggests that stroke triggers epigenetic changes that suppress SHMT1 expression, prompting compensatory metabolic responses to normalize folate-dependent one-carbon metabolism and manage toxic homocysteine accumulation." (PMID 40950018, 2025). "The SHMT1 methylation levels were significantly higher in the stroke patients (58.82 ± 17.83%) than in the controls (42.59 ± 20.76%, p < 0.001)." (PMID 33259775, 2021).
adenoma (2 papers, 2012). A neoplasm arising from the epithelium. "Remarkably, AAP-S and SHMT1 were both found clearly upregulated in these adenoma samples." (PMID 23154538, 2012). "In adenoma, both AAP-S and SHMT1 were present in higher concentration compared to normal thyroid tissue, showing that these proteins are upregulated in the tumor state." (PMID 23154538, 2012). "In our study the Shmt1 heterozygous ApcMin mice also have the largest mean amount of adenomas, albeit we did not investigate the impact of diet on this model." (PMID 22438825, 2012). "Interestingly, homozygous deletion of Shmt1 did not impact adenoma formation in ApcMin mice since there was a compensatory increase in thymidylate kinase (TK1) expression: a salvage pathway for thymidine synthesis." (PMID 22438825, 2012).
B cell lymphoma (2 papers, 2011 to 2012). "Taken together, we would argue that Shmt1 is a tumor-suppressing modifier in the context of B-cell lymphomas and colorectal adenomas." (PMID 22438825, 2012).
bladder cancer (2 papers, 2024 to 2025). "Although the T24 cell line was selected based on its typical low expression of miR-944 and high expression of SHMT1, future studies need to validate these findings in more bladder cancer cell lines such as HT-1376 and 5637 to further improve the reliability and generalization of the findings." (PMID 40442541, 2025). "Considering the existing data, previous bioinformatics analysis, and transcriptome sequencing results, it can be inferred that SHMT2, one of the two isozyme genes of serine hydroxymethyltransferase, is more likely to be a potential driver of bladder cancer than SHMT1." (PMID 38594513, 2024). "However, the impact of SHMT1/2 on the biological progression of bladder cancer and its molecular regulation mechanism remain unclear." (PMID 38594513, 2024).
fetal growth restriction (2 papers, 2021 to 2022). A fetus that does not grow beyond the 10th percentile of conventionally accepted weight for gestational age. "Understanding the role of the SHMT1 gene polymorphisms in the process of intrauterine growth restriction is important for the development of effective methods for the diagnosis and prevention of this pregnancy complication." (PMID 35098008, 2021).
glioma (2 papers, 2021 to 2022). A benign or malignant brain and spinal cord tumor that arises from glial cells (astrocytes, oligodendrocytes, ependymal cells). "The activity of SHMT1 was strongly negatively correlated with the overall survival in both clustering analysis and SGMRS analysis, which was accordance with previous study and endorsed the critical role of SHMT1 on the prognosis of glioma patients." (PMID 36467068, 2022). "Compared to the other clusters, gliomas in cluster 4 expresses significantly higher levels of PSPH and SHMT1 which were known culprits of aberrant serine and glycine production in malignant cancers." (PMID 36467068, 2022). "Further univariate analysis demonstrated that SHMT1, SARDH, and PSPH were hazardous prognostic factors for glioma." (PMID 36467068, 2022).
metabolic syndrome (2 papers, 2024 to 2025). A cluster of metabolic risk factors for CARDIOVASCULAR DISEASES and TYPE 2 DIABETES MELLITUS. "In contrast, SHMT1 influences lipid metabolism through DNA methylation and adipocyte differentiation in metabolic diseases such as obesity and metabolic syndrome, whereas SHMT2 regulates mitochondrial function, glycine metabolism, and oxidative stress resistance." (PMID 40738465, 2025). "Upon conducting a more in-depth analysis of SHMT1, which encodes the cytosolic counterpart of SHMT2, it was observed that the SHMT1 gene SNPs are also significantly associated with human metabolic phenotypes that define metabolic syndrome." (PMID 38347107, 2024).
Obesity (2 papers, 2023 to 2025). Accumulation of substantial excess body fat. "Our data showed that active beige adipocytes carrying FTO obesity-risk genotype expressed lower level of SHMT1 as compared to risk-free allele carrier ones suggesting lower generation of one-carbon units in thermogenic adipocytes with FTO obesity-risk genotype." (PMID 37416800, 2023). "We also revealed that one-carbon metabolism pathway, in which SHMT1 and GPT2 participate, was less expressed in active beige adipocytes with FTO obesity-risk alleles." (PMID 37416800, 2023). "In contrast, SHMT1 and SHMT2 influence adipose tissue methylation and energy metabolism via distinct mechanisms during the development of obesity." (PMID 40738465, 2025).
osteosarcoma (2 papers, 2012 to 2022). A usually aggressive malignant bone-forming mesenchymal neoplasm, predominantly affecting adolescents and young adults. "Of note, overexpression of genes belonging to the amplified region (COPS3, PMP22, GID4, ARGHAP44, TOP3A, SHMT1, and RASD1) was studied in osteosarcoma cell lines." (PMID 35920001, 2022). "Based on our statistical analysis of the correlation between copy number increase and expression level for each of the top ranking genes, we identified RICH2, c17orf45, TOP3A, COPS3, SHMT1, PRPSAP2, PMP22, and RASD1 as candidate osteosarcoma oncogenes in the 17p11.2-p12 region." (PMID 22292074, 2012). "However, prognostic studies for the other candidate genes require the development of new antibodies (C17orf39, RICH2, RASD1) or testing of available antibodies on osteosarcoma tissues (TOP3A, COPS3, SHMT1, PRPSAP2, PMP22), which is presently underway." (PMID 22292074, 2012).
small cell lung carcinoma (2 papers, 2022 to 2025). Small cell lung cancer (SCLC) is a highly aggressive malignant neoplasm, accounting for 10-15% of lung cancer cases, characterized byrapid growth, and early metastasis. "Additionally, plasma proteomic screening results indicated that SHMT1 plays a role in facilitating metabolic adaptation in small-cell lung cancer (SCLC)." (PMID 40738465, 2025).
thyroid cancer (2 papers, 2025). "In a previous study, we found that thyroid cancer cells become fully auxotrophic for glycine upon inhibition of SHMT1/2 with SHIN1." (PMID 40698729, 2025). "SHMT1 exhibits subtype-specific expression patterns in thyroid cancer." (PMID 40738465, 2025).
anaplastic thyroid cancer (1 paper, 2025). "In previous studies, we have shown that inhibition of one-carbon metabolism at SHMT1/2 in anaplastic thyroid cancer cells leads to glycine auxotrophy and rapid cell death when cells are deprived of extracellular glycine." (PMID 40698729, 2025).
cleft palate (1 paper, 2022). Cleft palate is a fissure type embryopathy that affects the soft and hard palate to varying degrees. "Other authors suggested that the lower activity of SHMT1 associated with the T allele may lead to folate retention in the cytoplasm that could ensure its availability, thus reducing the risks of cleft palate associated with a deficiency of folate." (PMID 36232598, 2022).
congenital heart defects (1 paper, 2021). "Furthermore, genetic variants of SHMT1, BHMT, MGST1, MGMT, MTHFS, GNMT, and TRDMT1 were associated with an increased risk of congenital heart defects after prenatal antidepressant exposure." (PMID 33981330, 2021).
deficiencies (1 paper, 2023). "In mice, however, Shmt1 knockout animals are a genetic model of folate deficiencies." (PMID 36627750, 2023).
diffuse large B-cell lymphoma (1 paper, 2025). "It has been recently reported that a small-molecule dual inhibitor of human SHMT1/2 could inhibit cancer cell survival through suppressing glycine demand, especially in diffuse large B-cell lymphoma." (PMID 40432803, 2025).
esophageal squamous cell carcinoma (1 paper, 2010). Esophageal squamous cell carcinoma (ESCC) is a type of esophageal carcinoma (EC) that can affect any part of the esophagus, but is usually located in the upper or middle third. "Recently, it was observed that in a North Chinese population there was a reduced risk of esophageal squamous cell carcinoma and gastric cardia adenocarcinoma in the case of SHMT1 1420CT heterozygotes compared to C homozygotes." (PMID 20920350, 2010).
Ewing sarcoma (1 paper, 2025). A small round cell tumor that lacks morphologic, immunohistochemical, and electron microscopic evidence of neuroectodermal differentiation. "This strongly suggests that upon prolonged inhibition of one-carbon metabolism at SHMT1/2, purine depletion is accompanied by deficiencies in additional metabolites or biological processes, which become limiting for Ewing sarcoma cell proliferation." (PMID 40698729, 2025). "To further define the relative impact of inhibiting one-carbon metabolism on these cytosolic pathways in Ewing sarcoma cells, we first tested whether providing exogenous metabolites can rescue cells from the growth suppression caused by pharmacologic inhibition of SHMT1 and SHMT2." (PMID 40698729, 2025). "To define the biological consequences of the overexpression of one-carbon metabolism genes, we generated two Ewing sarcoma cell lines (SK-ES-1 and TC-71) expressing control shRNAs or shRNAs targeting SHMT1 or SHMT2." (PMID 40698729, 2025). "Thus, inhibition of one-carbon metabolism in Ewing sarcoma cells leads to a near-complete cessation of the synthesis of glycine and purines with SHMT1/2 inhibitors and a significant impairment with DHFR inhibition, which has its major impact on dTTP synthesis." (PMID 40698729, 2025). "In line with the results of the short-term cell proliferation assays, shRNA-mediated depletion of SHMT1 did not alter the ability of Ewing sarcoma cells to form colonies." (PMID 40698729, 2025). "shRNA-mediated depletion of SHMT1 did not alter the proliferation of Ewing sarcoma cells." (PMID 40698729, 2025).
hyperphosphatemia (1 paper, 2022). Abnormally high level of phosphate in the blood. "Cytosolic serine hydroxymethyltransferase (SHMT1) is implicated in calcification of VSMCs in hyperphosphatemia, such as in chronic kidney disease." (PMID 35614104, 2022).
Insulin resistance (1 paper, 2019). Increased resistance towards insulin, that is, diminished effectiveness of insulin in reducing blood glucose levels. "Serine hydroxymethyltransferase 1 (SHMT1), ALDOC, SDSL, ASS1, and IDH3A are novel biomarkers for the development of insulin resistance." (PMID 30678306, 2019).
intestinal tumors (1 paper, 2018). "The Shmt1+/− mouse model is sensitized to folate-responsive NTDs and causes increased intestinal tumor formation when crossed to the ApcMin/+ mouse model." (PMID 29955725, 2018). "When the Shmt1+–- mouse was crossed to the ApcMin/+ mouse model [a mouse model lacking one copy of the adenomatosis polypsis coli (APC) gene], which spontaneously forms intestinal tumors, mice heterozygous for both Shmt1 and the Min allele showed increased total intestinal tumors." (PMID 29955725, 2018). "Total intestinal tumors were analyzed and biomarkers of folate status and metabolism were measured, including plasma folate concentrations, colon uracil content, and SHMT1 concentrations." (PMID 29955725, 2018). "Shmt1+/−ApcMin/+ mice fed FD diets have increased total intestinal tumors and increased uracil in colon DNA relative to Shmt1+/+ApcMin/+ mice, suggesting a relation between Shmt1 heterozygosity, folate status, uracil in DNA, and intestinal tumorigenesis." (PMID 29955725, 2018).
lacrimal gland adenoid cystic carcinoma (1 paper, 2019). A adenoid cystic carcinoma that involves the lacrimal gland. "In lacrimal gland adenoid cystic carcinoma, SHMT1 overexpression was correlated with poor prognosis." (PMID 30755243, 2019).
leukemia (1 paper, 2022). A malignant (clonal) hematologic disorder, involving hematopoietic stem cells and characterized by the presence of primitive or atypical myeloid or lymphoid cells in the bone marrow and the blood. "Loss of both SHMT1 and SHMT2 was necessary for impaired growth and cell cycle arrest, with suppression of both SHMT1 and SHMT2 inhibiting leukemia progression in vivo." (PMID 34341479, 2022). "Redundancy of SHMT1 and SHMT2 enzymes has been shown in HEK293T and HCT-116 cells, though it is unclear if this occurs in leukemia." (PMID 34341479, 2022).
liver cancer (1 paper, 2016). An epithelial or non-epithelial malignant neoplasm that arises from the liver. "Forty-seven primary liver cancer patients were genotyped for ten polymorphisms: DHFR 19bp ins/del, TS 2rpt-3rpt, MTHFD1 1958G>A, MTHFR 677C>T, MTR 2756A>G, MTRR 66A>G, RFC1 80G>A, SHMT1 1420C>T, BHMT 716 A>G, TC II 776C>G." (PMID 27936032, 2016).
medullary thyroid carcinomas (1 paper, 2025). "Immunohistochemical analysis of 557 tumor samples revealed that SHMT1 expression was significantly elevated in PTC and poorly differentiated thyroid carcinoma, but was lowest in medullary thyroid carcinoma." (PMID 40738465, 2025). "In contrast, SHMT1 expression was low or absent in follicular and medullary thyroid carcinomas." (PMID 40738465, 2025).
melanoma (1 paper, 2023). A malignant, usually aggressive tumor composed of atypical, neoplastic melanocytes. "Additionally, lower expression of SHMT1/2 was related to longer survival in melanoma patients treated with anti-PD1 immunotherapy." (PMID 37223471, 2023). "Similarly, in the PRJEB23709 melanoma anti-PD1 immunotherapy cohort, the levels of PSAT1, PSPH, and SHMT1/2 were significantly reduced in PR or CR patients treated with anti-PD1 compared with drug-resistant PD patients." (PMID 37223471, 2023).
multiple myelomas (1 paper, 2012). "Overexpression of SHMT1 and PRPSAP2 (and also COPS3) has been reported to occur in multiple myelomas." (PMID 22292074, 2012).
multiple sclerosis (1 paper, 2026). A progressive autoimmune disorder affecting the central nervous system resulting in demyelination. "Together, these data suggest that GQ/iM structures are necessary for SHMT1 regulation, which could serve as a target for therapeutic intervention for multiple sclerosis patients." (PMID 41939317, 2026). "Serine hydroxymethyltransferase 1 (SHMT1) is a key player in DNA methylation and was determined to be upregulated in multiple sclerosis patients." (PMID 41939317, 2026).
ovarian tumor (1 paper, 2017). "In complete agreement with our soft-agar results, we found that loss of SHMT1 inhibited ovarian tumor growth in vivo." (PMID 28288142, 2017).
pancreatic adenocarcinoma (1 paper, 2019). "Combining with clinical data, we analyzed the mRNA expression levels of PHGDH and SHMT1 in clinical samples from The Cancer Genome Atlas (TCGA) pancreatic adenocarcinoma cohort." (PMID 30744688, 2019).
Sepsis (1 paper, 2022). Sepsis is defined as life-threatening organ dysfunction caused by a dysregulated host response to infection. "Given that sepsis dysregulates glycine metabolism in mice, we examined whether DCA might blunt glycine deficiency during sepsis by assessing GNMT, SARDH, SHMT1, and SHMT2, the key enzymes involved in glycine metabolism." (PMID 35730570, 2022).
serous ovarian cancer (1 paper, 2023). "These included several upregulated proteins previously identified in high-grade serous ovarian cancer (SHMT1, TAGLN)." (PMID 38014221, 2023).